IL1B (interleukin 1 beta)
Diseases named in the same sentence as IL1B in open-access papers (continued):
Sharing a sentence is not in itself a finding about the gene and the disease.
sarcopenia (continued). "The classifier accuracy for the E-DII + IL-1β model was approx. 80%, which renders it a reliable index to distinguish healthy individuals from sarcopenia patients." (PMID 41345186, 2025). "The available reports on changes in concentrations of CRP, IL-1β, IL-6 and TNFα confirmed that inflammation was a critical component of sarcopenia progression." (PMID 41345186, 2025). "Research has identified elevated levels of pro-inflammatory cytokines such as interleukin-6 (IL-6), interleukin-8 (IL-8), tumor necrosis factor-alpha (TNF-α), and IL-1β in individuals with sarcopenia." (PMID 40943447, 2025). "For example, in sarcopenia, it was found that the reduction in muscle mass was associated with an increase in the secretion of IL-6, TNF-α, and IL-1β by the intramuscular adipose tissue." (PMID 40001498, 2025). "When NLRP3 is activated, impaired autophagy results in elevated IL-1β expression, which triggers the NF-κB signaling pathway, exacerbating the onset of sarcopenia." (PMID 39588187, 2024). "Currently, there is relatively limited research on IL-1β and sarcopenia, but studies have shown its potential correlation with grip strength." (PMID 39101140, 2024). "Elevated levels of IL-6, IL-1β, TNF-α, and C-reactive protein (CRP) have been implicated in the loss of muscle mass and strength in sarcopenia." (PMID 39101140, 2024). "Our review of the available literature proved that the relationship of sarcopenia and IL-1β had been scarcely investigated." (PMID 37465171, 2023). "A notable discovery has been made regarding the reduction of TNF-α, IL-1β, and IL-6 levels following exercise and nutritional support in individuals diagnosed with sarcopenia." (PMID 38032288, 2023). "Our study found an association between sarcopenia and certain inflammatory mediators as CRP, albumin, CRP/albumin ratio, IL-1β, and cfDNA." (PMID 37465171, 2023). "Adipose tissue is a significant source of proinflammatory cytokines, such as IL-1β and IL-6, both probably involved in the development of sarcopenia, and TNF-α." (PMID 37373124, 2023). "This field of research will also hopefully lead to new and specific therapies able to affect the deleterious consequences of the NLRP3 inflammasome-IL-1β/18 pathway activation in sarcopenia." (PMID 33808510, 2021). "These cytokines, viz., IL-6, TNF-α, and IL-1β, activate muscle-specific protein degradation pathways through E3 ubiquitin ligases TRIM63 and FBXO32, linking NSCLC progression to cancer-associated sarcopenia." (PMID 42278237, 2026). "NLRP3 and Myd-88 are key orchestrators of chemotherapy-related cardiovascular diseases (CTRCD) and sarcopenia; cytotoxic properties are principally mediated by high levels of pro-inflammatory cytokines and chemokines, such as IL-1β, IL-6, IL-8, CXCL-2, TGF-β, IL-18 and others." (PMID 38672567, 2024). "Our research may indicate a potential use of IL-1β as an indicator of sarcopenia (AUC for IL-1β was 0.690), however, more research should be conducted to confirm this relationship." (PMID 37465171, 2023). "In this study, significantly higher values of IL-1β were detected in the sarcopenia group." (PMID 37465171, 2023). "One of the diverse mechanisms known to contribute to the onset of sarcopenia is the slight but persistent increase in inflammatory mediators such as IL-1β, IL-6, and TNF-α that simultaneously impact muscle metabolism, causing wasting and loss via the mTOR pathway." (PMID 35954203, 2022). "Similarly, IL‐1β and TNF‐α were positively associated (P < 0.05) with the presence of sarcopenia, while a trend existed for both IL‐6 (P = 0.06) and IL‐8 (P = 0.09)." (PMID 35080147, 2022). "Although IL-1β may be considered a reliable inflammatory biomarker of physiological decline, some reports have found that IL-1β is downregulated in frailty and sarcopenia." (PMID 33815869, 2021).
sarcopenia (continued). "Moreover, a 10-year clinical tracking survey also suggested that the serum concentrations of IL-1β, IL-6 and TNF-α are closely associated with morbidity and mortality in older sarcopenia patients." (PMID 32226296, 2020). "Therefore, we suggest that the increased atrogin-1 and MuRF-1 expression as well as a proportion of the sarcopenia observed in AiA rabbits may have been driven by direct autocrine IL-1β signaling." (PMID 28740214, 2017). "Interleukins exert a pivotal role in sarcopenia, with elevated TNF-α, IL-6, and IL-1β levels correlating with increased mortality and morbidity among older adults." (PMID 40429815, 2025). "Of these, pro-inflammatory factors [tumor necrosis factor (TNF-α), interleukin (IL-1β), and interferon (IFN-γ)] can inhibit the expression of growth hormone and promote the occurrence of sarcopenia." (PMID 41164369, 2025). "Elevated levels of IL-6, IL-1β, TNF-α, and CRP have been identified as potential contributors to the unfavorable outcomes of sarcopenia in PD-1 inhibitor treatment." (PMID 39101140, 2024). "The GEE analysis adjusted by age and gender revealed sarcopenia significantly elevated TNF-α (p=0.003), IL-1β (p=0.001) and IL-6 (p<0.001), whereas intervention led to a decrease in TNF-α (p=0.005) and IL-1β (p=0.017) and an increase in IL-15 (p=0.024)." (PMID 38032288, 2023). "Our study result was in line with the previous animal and clinical studies, highlighting sarcopenia to be a pro-inflammatory status leading to elevated TNF-α, IL-1β, and IL-6." (PMID 38032288, 2023). "The study discovered that patients with sarcopenia exhibit elevated levels of TNF-α, IL-1β and IL-6." (PMID 38032288, 2023). "Firstly, it has been observed that patients with sarcopenia exhibit elevated levels of inflammatory cytokines such as TNF-α, IL-1β, and IL-6." (PMID 38032288, 2023). "We observed that the expression of IL1B, BAK1 and SOD1 were significantly increased, while the expression of CDH1, GNG11 and ZAP70 were dramatically decreased in sarcopenia samples compared to those in the controls." (PMID 32226296, 2020). "For the models of E-DII and inflammatory mediators, AUC measurements for E-DII + cfDNA (AUC = 0.805) were considered a good discrimination, and the evaluation was as acceptable for cytokines IL-1β, IL-6, TNFα and CRP (0.7 < AUC < 0.8) i.e., it enabled sarcopenia diagnosis." (PMID 41345186, 2025). "In our study, we noted lower values of inflammatory markers (CRP, CRP/albumin ratio, TNFα, IL-6, IL-1β, cfDNA) in the no-sarcopenia group, as opposed to the sarcopenia group." (PMID 37465171, 2023). "C-reactive protein (CRP) (p = 0.011) and CRP/albumin ratio (p = 0.030) as well as IL-1β (p = 0.002), cfDNA (p < 0.001) and bilirubin levels (p = 0.002) were significantly higher in the sarcopenia group as opposed to the no sarcopenia group." (PMID 37465171, 2023). "The results of the ROC analysis of the indicators which are likely to be important in the diagnosis of the inflammaging in sarcopenia, i.e., cfDNA, CRP and IL-1β ranged from 0.6 to 0.7, which can be considered as a potential diagnostic value for clinical prognosis for older patients." (PMID 37465171, 2023). "In the Copenhagen sarcopenia study, elderly women also had significantly higher levels of CRP, TNF-α, and IL-6, compared with middle-aged women and significantly higher levels of CRP, TNF-α, IL-1β, and IL-4 compared with young girls." (PMID 36291982, 2022). "The average levels of the four proinflammatory cytokines, including IL-1β, IL-6, IL-15, and TNF-α, were significantly increased in sarcopenia patients compared to those in young/healthy volunteers, while the concentrations of two other cytokines, IL-4 and IL-13, were not changed." (PMID 32226296, 2020). "Third, specific pro-inflammatory cytokines such as IL-6, TNF-α, and IL-1β–known to play direct roles in the pathogenesis of sarcopenia—were not available in the NHANES dataset and, thus could not be analyzed." (PMID 40708651, 2025).
sarcopenia (continued). "The concentration of IL-1β was significantly higher in the group with sarcopenia than without the condition and negatively correlated with the gait speed (rs = −0.263, p < 0.01) which, in turn, points to the relation of inflammation with the functional impartment in old age." (PMID 37465171, 2023). "Moreover, after reviewing the studies focusing on the relationships between cytokines, growth factors and sarcopenia, many factors, including IL1b, IL6, IL8, IL17 (interleukin‐17), TNFa, TGF1, GDF‐15 (growth differentiation factor‐15) and so on, may all relate to sarcopenia." (PMID 38556722, 2024). "This hypothesis is supported by various studies that have demonstrated that IL1β, after being activated by NLRP3 inflammasome, plays a crucial role in the onset and disease progression of several myopathies, such as myositis, sarcopenia and Duchenne muscular dystrophy." (PMID 33802349, 2021). "The area under curve of the ROC analysis to discriminate participants with and those without sarcopenia was 0.65 (95% CI, 0.54-0.75) for TNF-α, 0.74 (95% CI, 0.65-0.84) for IL-1β, 0.80 (95% CI, 0.71-0.88) for IL-6 and 0.55 (95% CI, 0.44-0.66) for IL-15." (PMID 38032288, 2023). "Meanwhile, IL-1β and TNF-α serum levels did not correlate with sarcopenia status." (PMID 30513776, 2018).
Chronic colitis (48 papers, 2013 to 2025). A chronic inflammatory disease of the large intestine (colon, cecum and rectum). "By contrast, in animal models of chronic colitis, the inflammasome-induced IL-1β release induces differentiation of T cells into pathogenic Th17 phenotypes, thus contributing to sustain the inflammatory process." (PMID 28179906, 2017). "This system released over 70% of 5-ASA within 6–16 h at pH 7.0 and demonstrated therapeutic efficacy in a chronic colitis mouse model by significantly reducing the expression of IL-1β and TNF-α, as well as inflammatory markers such as MPO, H2O2, and MDA." (PMID 41219776, 2025). "From the perspective of cytokine expression, qPCR analysis demonstrated that the upregulation of Il1b, Tnfa, and Il6 were diminished in Tmem173iΔmye mice in both acute and chronic colitis." (PMID 39113810, 2024). "In accordance with acute colitis, proinflammatory factor levels (e.g., IFN-γ, TNF-α, IL-17A, IL-1β and IL-6) were obviously elevated in chronic colitis mice compared to those of normal mice." (PMID 38396052, 2024). "In the present study, colonic inflammation was evident in mice with DSS-induced chronic colitis and elevated levels of IL-6 and IL-1β." (PMID 37695333, 2024). "This work found that chronic colitis resulted in increased myeloperoxidase activity in the colon, as well as increased levels of proinflammatory cytokines IL-1β and CXCL1." (PMID 37512580, 2023). "The elevation of IL-1β and IL-18 levels suggests inflammasome activation, which is believed to be involved in chronic colitis." (PMID 37513865, 2023). "The data demonstrated a significant increase in IL-1β expression in mice induced with chronic colitis and fed −I3C, and this increase was attenuated with the addition of dietary I3C." (PMID 38068838, 2023). "The magnitude of the changes in IL-1β levels we observed are similar to that observed in the hippocampus in chronic colitis and in febrile seizures." (PMID 35379260, 2022). "IL-1β is a key instigator of inflammation and accumulates in the intestinal mucosa of chronic colitis models as it is secreted by infiltrating macrophages." (PMID 35126813, 2022). "Our results indicate that chronic colitis upregulates IL-1β augmenting certain cardiac miRNAs, particularly miR-155, which leads to suppression of BDNF corresponding to impaired heart function." (PMID 34543287, 2021). "The significance of IL-1β in the chronic colitis model was reinforced when DSS-induced augmentation of miR-155 expression was shown to be reversed with IL-1β neutralizing antibody." (PMID 34543287, 2021). "Consistent with other reports of chronic colitis, two key markers of chronic colitis IL-1β and TNFα were significantly elevated in PBS-treated mice when compared to healthy animals." (PMID 31756977, 2019). "In addition, in a study using a chronic colitis mice model, IL-10 suppressed the inflammasome/IL-1β pathway, reduced the pathogenicity of Th17 cells, and suppressed IL-17 production, leading to the mitigation of intestinal inflammation." (PMID 37894114, 2023). "Moreover, CR attenuated chronic colitis in mice in a dosing time-dependent manner based on measurements of disease activity index, colon length, malondialdehyde/myeloperoxidase activities and IL-1β/IL-6 levels." (PMID 34393786, 2021). "Moreover, SSW might decrease the expressions of IFN-γ, IL-1β, and IL-17, upregulate the level of IL-4, and show therapeutic effects in chronic colitis." (PMID 34956391, 2021). "After the induction of chronic colitis, a substantial elevation in the levels of iNOS, COX-2, TNF-α, IL-6, and IL-1β were observed in this study." (PMID 37891901, 2023). "The mRNA expression levels of inflammatory cytokines including IFN-β, IL-1β, IL-6, iNOS, MCP-1, and TNF-α were high in AOM+DSS induced chronic colitis group." (PMID 33995655, 2021). "The effect of CR on chronic colitis was accessed based on DAI, colon length, MDA/MPO activities and IL-1β/IL-6 levels as well as histopathological analysis." (PMID 34393786, 2021).
Chronic colitis (continued). "In contrast, B. lactis LA804 which was less efficacious in the acute model was the most protective against chronic colitis by downregulating the expression of genes for CXCL2, IL-1β and TNF-α in TNBS-treated mice." (PMID 31035617, 2019). "Levels of the inflammatory cytokinesTNF-α, IL-1β, IL-6, MCP-1, and CSF-1 and of COX-2 were measured in mice with chronic colitis." (PMID 29245972, 2017). "Colorectal mRNA levels of inflammatory cytokines TNF-α, IL-1β, IL-6, MCP-1, and CSF-1, and COX-2, were measured in mice with chronic colitis." (PMID 27557503, 2016). "Enzyme-linked immunosorbent assay (ELISA) revealed lower protein levels of pro-inflammatory cytokines, including TNF-α, IL-1β and IFN-γ, in colon tissues of mice with DSS-induced acute and chronic colitis that received HQT." (PMID 27982094, 2016). "Detection of the cytokine concentrations in the supernatant (five samples per group) revealed that IL-1β, IL-6, IL-12p70, TNF-α, and IL-23 were significantly decreased in the chronic colitis + Se-enriched L. acidophilus group compared with the chronic colitis group (P < 0.05)." (PMID 34532332, 2021). "In the present study, significant increases in the production of IL-6, IL-12p70, IL-1β, TNF-α, IFN-γ, IL-21, and IL-17A and decreases in the production of IL-10 were observed in the chronic colitis group compared with the control group, and these changes were restored by NAM treatment." (PMID 33748287, 2021). "In our results, we established a refined and translationally relevant model of DSS chronic colitis in C57BL/6 mice and found morbidity in liver morphology and significant increases in proinflammatory cytokines (TNF-α, IL-1β, and IL-6) in the liver tissue of IBD mice." (PMID 33029104, 2020). "In a spontaneous chronic colitis mouse model (Winnie mice), MCC950 reportedly attenuated colonic inflammation, as assessed by significant improvements in body weight and colon length, accompanied by reduced IL-1β secondsretion." (PMID 30823406, 2019). "Measurement of cytokine concentrations in the culture supernatants of the MLN without any stimulation manifested that the levels of IL-6, IL-1β, and IL-23 were sharply decreased in the IL-33-treated chronic colitis group compared with the control group." (PMID 30539029, 2018). "In addition, our study revealed a negative correlation between the levels of β-hydroxybutyrate in rats with chronic colitis and proinflammatory cytokines such as TNF-α, IL-6, IL-1β, and IL-18, with a strong tendency towards a positive correlation with IL-10 levels." (PMID 37513865, 2023). "Results demonstrated that administration of PADF (10 mg/Kg/day) to mice with DSS chronic colitis significantly reversed the colon shortening, reduced the histological damage, neutrophil infiltration (as showed by MPO activity assay), and the production of inflammatory cytokines (IL-1β and TNF-α)." (PMID 32033338, 2020).
lung adenocarcinoma (48 papers, 2011 to 2025). A carcinoma that arises from the lung and is characterized by the presence of malignant glandular epithelial cells. "This oral commensal has previously been linked to immunosuppression in lung adenocarcinoma through the β-glucan/Dectin-1/CARD9/IL-1β axis." (PMID 40391887, 2025). "We identified novel cancer‐associated secretory (CAS) cells and interleukin (IL)‐1β+ macrophages as key contributors to the progression of lung adenocarcinoma (LUAD) exhibiting part‐solid radiological features in female never‐smokers." (PMID 40824728, 2025). "Stem cell factor (SCF) (OR = 1.150, 95% CI: 1.021–1.296, P = 0.021) and interleukin-1beta (IL-1β) (OR = 1.152, 95% CI: 1.003–1.325, P = 0.046) were positively associated with the risk of lung adenocarcinoma." (PMID 38957317, 2024). "We incubated HBEC-3KT and HSAEC-1KT, as well as the 7 lung adenocarcinoma cells of varying driver mutations with 5 ng/mL IL-1β for 48 h and performed RT-qPCR, Western blotting, and cell viability assays to determine their response to IL-1β." (PMID 37985999, 2023). "Here, we show that IL-1β-stimulated lung adenocarcinoma cells with various driver mutations respond with an NFκB-mediated upregulation of IDO1." (PMID 37985999, 2023). "The NLRP3 inflammasome enhances lung adenocarcinoma cell A549 proliferation by activating the IL-1β/ERK/CREB and IL-18/AKT/CREK signaling pathways." (PMID 40026444, 2025). "In IR-silenced lung adenocarcinoma, the expression of the IL-1B gene exhibited a positive correlation with the ERK signaling pathway." (PMID 39911279, 2025). "The concurrent inhibition of IL-1β/miR-144-3p/WT1D by a miR-144-3p mimic and IL-1β/NF-κB/COX-2/HIF-1α by celecoxib suppresses lung adenocarcinoma cell growth with a synergistic effect." (PMID 37460927, 2023). "Here, we provide novel insights on a mechanism that plausibly underlies this effect: namely the induction of immune checkpoint protein IDO1 by IL-1β in lung adenocarcinoma cells." (PMID 37985999, 2023). "With the aid of TIMER2.0 database, we found that TRAF3 was positively correlated with the expression of ASC (R = 0.09, P<0.05), caspase-1 (R = 0.32, P<0.01) and IL-1β (R = 0.37, P<0.01) in lung adenocarcinoma." (PMID 37798663, 2023). "Upon IL-1β stimulation, lung adenocarcinoma cells exhibited significant increases in IDO1 mRNA and protein levels, a response that depended on the NFκB pathway." (PMID 37985999, 2023). "Remarkably, IL-1β also upregulated the expression of programmed death ligand-1 (PD-L1) and PD-L2 in multiple cell lines, indicating that IL-1β triggers parallel immune-suppressive mechanisms in lung adenocarcinoma cells." (PMID 37985999, 2023). "Interleukin-1β (IL-1β) plays a vital role in the transformation between inflammation and cancer in lung adenocarcinoma via the IL-1β/NF-κB/COX-2/HIF-1α axis." (PMID 37460927, 2023). "We first analyzed the correlation between TRAF3 and pyroptosis-related genes through TIMER2.0 database, the results showed that TRAF3 was positively correlated with the expression of ASC, caspase-1 and IL-1β in lung adenocarcinoma." (PMID 37798663, 2023). "Our study has identified IL-1β as an upstream regulator of IDO1/PD-L1 axis of immune suppression in lung adenocarcinoma cells, which is partly through NFκB-p65 activity." (PMID 37985999, 2023). "IL-1β also promotes glycolysis in lung adenocarcinoma cells via the p38 axis, which further enhances lung adenocarcinoma cell migration and invasion." (PMID 36588722, 2022).